CD4 (CD4 molecule)
Diseases named in the same sentence as CD4 in open-access papers (continued):
Sharing a sentence is not in itself a finding about the gene and the disease.
vitiligo (continued). "Adoptive transfer of CD4+ T cells from Ag-GILT+/+Tg mice leads to rapid vitiligo in Ag-expressing RAG1-/- recipients with a median onset of five weeks, consistent with previous findings." (PMID 25875653, 2015). "In the current study, a significant positive correlation was observed between the peripheral percentage of FoxP3+ cells and that of CD4+CD25+ T cells in vitiligo patients." (PMID 26788051, 2015). "Decreased CD4+ to CD8+ lymphocytes ratio in vitiligo-stricken skin compared to healthy skin and CD8 T cells directed against melanocytic antigens have been found both in perilesional skin and in the blood of vitiligo patients." (PMID 26457199, 2015). "Further, in vitro direct analysis of margins of vitiliginous skin showed polarized type 1 T cells (CD4+ and particularly CD8+) that predominantly secrete IFN-γ and TNF-α cytokines that are associated with the destruction of melanocytes during active vitiligo." (PMID 26442157, 2015). "Our findings are consistent with a recent report from Ben Ahmed in which the suppressive effects of peripheral CD4+ CD25+ T regulatory cells on conventional CD4+ CD25− T cell proliferation were analyzed in vitiligo patients." (PMID 22649532, 2012). "Other studies have shown an increase in CD4+ T-lymphocytes in addition to an elevated CD4+/CD8+ ratio in vitiligo patients, a finding that is present in patients with autoimmune thyroid disease." (PMID 22099887, 2011). "CD4 T cells have also been found to infiltrate vitiligo lesions, although less is known about melanocyte-specific CD4 T cell responses." (PMID 21911918, 2011). "Furthermore, relatively limited advances have focused on the involvement of CD4+ helper T cell (Th) immunity in vitiligo." (PMID 40725033, 2025). "AhR activation enhanced IL-22 release in CD4+ T cells of vitiligo patients." (PMID 38361944, 2024). "Vitiligo has also been thought to be caused by melanocyte-specific cytotoxic CD8+ T cell destruction, and though the absolute number of lymphocytes remains stable in vitiligo patients, the proportion of CD8+ T cells to CD4+ T cells is frequently increased." (PMID 38346060, 2024). "Subsequently, through a series of gain‐of‐function and loss‐of function experiments, we indicated that miR‐125b‐5p exerted the favorable effects on H2O2‐induced oxidative damage in vitiligo melanocytes, whereas miR‐132‐3p dramatically promoted the differentiation of Treg cells in CD4+ T cells." (PMID 38887870, 2024). "Our findings revealed that five hub genes were linked to the abundance of activated CD4+ and CD8+ T cells, CD56-bright NK cells, immature dendritic cells, mast cells, Tregs, Th2 cells, monocytes, and NK cells, all of which contribute to vitiligo pathogenesis." (PMID 37287971, 2023). "In addition to CD8 + T cells, many kinds of immune cell infiltration are found, including CD4+ Tcells, T-regulatory cells (Tregs), natural killer (NK) cells, dendritic cells, and skin resident T cells in the blood and skin lesions of vitiligo patients." (PMID 34107850, 2021). "PF is the main bioactive ingredient of total glycosides of paeony (TGP) and the latter could promote recovery of depigmentation in patients with vitiligo by increasing CD4+/CD8+ T lymphocyte ratio and CD4+CD25+ Treg cell level." (PMID 32410998, 2020). "Shi found that the relative proportion (% area) of CD4+ T cells in longitudinal sections of feather pulp changed over time from 0.61% in samples from non-vitiligo SL chickens, to 2.35% just before (<2 weeks) onset and 4.81% during active vitiligo." (PMID 33092272, 2020). "It is not known exactly what is the mechanism of action of tacrolimus in vitiligo, but in an immunohistochemical study with 0.1% tacrolimus in vitiligo induced by the Köbner phenomenon, a significant decrease was observed in the infiltration of CD4+ and CD8+ T lymphocytes." (PMID 33153826, 2020).
vitiligo (continued). "CD4+ T cells dominate the autoimmune response prior to and at onset of SLV, whereas progression of vitiligo and melanocyte loss are associated with sustained presence of CD8+ T cells, which are also found in close association with apoptotic melanocytes in the barb ridge." (PMID 33092272, 2020). "The mechanism of action of corticosteroids in vitiligo has not yet been fully elucidated, but an immunohistochemical study with mometasone in vitiligo induced by Köbner phenomenon observed a significant decrease in the infiltration of CD4+ and CD8+ T lymphocytes." (PMID 33153826, 2020). "The percentage of peripheral FoxP3+ Tregs in vitiligo patients group ranged from 0.6% to 2.1% of CD4+ T cells with a mean of 1.09% ± 0.96% which was significantly lower than that of control group which ranged from 0.04% to 2.0% with a mean of 1.44% ± 0.24% (P < 0.05)." (PMID 26788051, 2015). "Our results showed a statistically significant decrease in the percentage of peripheral CD4+CD25+ T cells in vitiligo patients (range from 2.9% to 34% of CD4+ T cells with a mean of 11.49% ± 8.58%) compared to healthy controls (range from 17% to 27% with a mean of 21.20% ± 3.08%) with P value <0.05." (PMID 26788051, 2015). "The fact that animals receiving anti-NK1.1 therapy in addition to ACT experience vitiligo sooner than animals receiving ACT alone suggests that the adoptively transferred TRP-1-specific CD4+ T cells are rejecting TRP-1+ cells more quickly under these conditions." (PMID 26405570, 2015). "In vitro, direct analysis of skin T-cells from the margins of vitiliginous skin showed that polarized type-1 T cells (CD4+ and particularly CD8+), which predominantly secrete IFNG and TNFA are associated with the destruction of melanocytes during active vitiligo." (PMID 24312346, 2013). "In vitro, direct analysis of skin T cells from margins of vitiliginous skin show that polarized type-1 T cells (CD4+ and particularly CD8+), which predominantly secrete interferon (IFN)-γ and TNF-α are associated with the destruction of melanocytes during active vitiligo." (PMID 23284977, 2012). "The extent and severity of vitiligo was also unaltered by total CD4 T cell depletion." (PMID 22046294, 2011). "Two recent studies have identified increased levels of IL-17 in both the serum and tissue of vitiligo patients, which may suggest CD4 T cell involvement." (PMID 21911918, 2011). "In mixed vitiligo (segmental associated with non-segmental vitiligo; n = 3, 7.5%): A mild superficial lymphocytic infiltrate that included CD4 and CD8 lymphocytes and melanophages was frequently observed just below a lichenoid infiltrate around melanocytes in the epidermis." (PMID 39359912, 2024). "Similarly, CD4+ T lymphocytes infiltrate vitiligo lesions and may accelerate vitiligo development by releasing interferon (IFN)-γ." (PMID 37287971, 2023). "Indeed, AhR expression was significantly lower in CD4+ T cells and the skin of vitiligo patients than that in healthy controls, and knockdown of AhR increased IL-17A production and decreased IL-22 levels in CD4+ T cells of vitiligo patients." (PMID 35625824, 2022). "Notably, although not observed in the other groups, the group treated by ACT in the presence of CTXpre/CD4post (CTX/ex-T/anti-CD4 group) developed vitiligo, a sign of CD8+ T-cell-induced melanocyte destruction, indicating the increased response of CD8+ T cells." (PMID 34493727, 2021). "Considering the presence of PD-1+ CD4+ regulatory T cells in blood of vitiligo patients, PD-L1 fusion protein might give different results in the human setting, justifying further research on the effect of increased PD-1/PD-L1 signaling on both T cell subsets to determine treatment outcome." (PMID 33240267, 2020).
vitiligo (continued). "Because we have recently demonstrated that antigen liberated by autoimmune melanocyte destruction (i.e. vitiligo) supports functional CD8 memory T cell responses after Treg depletion and surgery, we first examined whether sustained depletion of CD4 T cells affected the development of vitiligo." (PMID 22046294, 2011). "Both miR-19b and 720 and have involved in the development of vitiligo through CD8+ and CD4+ T cell response." (PMID 39762270, 2025). "Mac‐InflamAP showed enhanced outgoing signaling to CD4+ T cells and CD8+ T cells in vitiligo samples, particularly through MHCII and MHC‐I and costimulatory pathways, suggesting its role in promoting T cell activation." (PMID 41498037, 2025). "MEL from vitiligo skins also exhibited an enhanced MHC‐I and CD4 singaling with CD4+ T cells compared to HCs, indicating intrinsic alternation of MEL in vitiligo pathology." (PMID 41498037, 2025). "Emerging evidence implicates the dysregulation of cellular immunity, particularly perturbations in CD4+ and CD8+ T lymphocytes, as a critical driver in the immunopathogenesis of vitiligo." (PMID 40725033, 2025). "IFN-γ is mainly derived from NK cells, CD4+ T lymphocytes, and activated CD8+ CTL; however, the main source of IFN-γ in vitiligo patients is CD8+ CTL." (PMID 39040109, 2024). "In a bioinformatics analysis, the number of activated CD4+ and CD8+ T cells and Th2 cells was significantly increased in vitiligo lesions compared to control skin samples." (PMID 38887286, 2024). "The authors further investigated the response of ex vivo cultured peripheral blood CD4+ and CD8+T cells from vitiligo patients to supernatant of H2O2-treated HaCaT." (PMID 37325658, 2023). "The reports on the detection of peripheral blood T lymphocyte subpopulation of vitiligo patients are different, and most studies hold that CD4+ T lymphocyte declines, CD8+ T lymphocyte rises and CD4+/ CD8+ lowers." (PMID 35035426, 2022). "CD4+ and CD8+ T lymphocyte expression level in the skin damage part of vitiligo patients and normal control group (x̅ ±s)." (PMID 35035426, 2022). "This study describes a mouse vitiligo model that induces epidermal depigmentation by the combination of B16F10 inoculation and anti-CD4 antibody administration." (PMID 36182982, 2022). "We have known that CD4+ and CD8+ T cells are present at the epidermal and dermal junctions near vitiligo lesions, and CD8+ T cells have been proven to induce melanocytes loss, underscoring the role of T cell-mediated immunity in the pathogenesis of vitiligo." (PMID 36439174, 2022). "Immune infiltration analysis demonstrated that CD4 T Cell, CD8 T Cell, Tregs, NK cells, dendritic cells, and macrophages were involved in vitiligo’s pathogenesis." (PMID 34107850, 2021). "CD4 T Cell, CD8 T Cell, Tregs, NK cells, dendritic cells, and macrophages are related to vitiligo occurrence." (PMID 34107850, 2021). "HLA-DQ cell surface expression on CD4+ and CD8+ T cells has been documented in health as well as in relation to both autoimmune conditions (for example T1D, CD and vitiligo) and infectious episodes." (PMID 32743532, 2020). "Preclinical studies have provided promising results when using polyclonal CD4+CD25+FoxP3+ Tregs to enforce immune tolerance in various mouse models, including vitiligo." (PMID 33335528, 2020). "The decreased CD4+/CD8+ ratio of skin-infiltrating T cells and CD8+ T cells from vitiligo skin are observed in progressive disease." (PMID 29456788, 2017). "Decreased CD4+/CD8+ ratio was shown in active generalized vitiligo patients, which is involved in the pathogenesis of vitiligo." (PMID 29456788, 2017). "CD8+ and CD4+ T cells in perilesional areas of non-segmental vitiligo exhibited a predominantly type-1-like cytokine profile, with secretion of IFN-γ and TNF-α8." (PMID 39762270, 2025). "Among the differentially expressed lncRNAs among T cells was LOC100506314 whose expression was enhanced in vitiligo, particularly in CD4+ T cells, but not in CD8+ T cells." (PMID 39881955, 2025).
vitiligo (continued). "The CD4+ TRM cells are present in the dermis, whereas melanocyte-specific CD8+ TRM are located in the epidermis of perilesional skin, near the melanocytes of patients with vitiligo." (PMID 35884944, 2022). "Serum CD4+ T cells of vitiligo patients reduced, compared with the normal control group (P<0.05), and CD4+/CD8+ declined (P<0.05)." (PMID 35035426, 2022). "CD4+ and CD8+ T lymphocyte expression level of vitiligo patients increased, compared with normal control group (p<0.05), and CD8+ T lymphocyte expression level of vitiligo patients increased, compared with normal control group (p<0.05, shown in Table-IV)." (PMID 35035426, 2022). "CD4 and CD8 T cells mainly produce IFN-γ and TNF-α in vitiligo." (PMID 34107850, 2021). "Given that PD-1 is expressed by both peripheral regulatory CD4+ and cytotoxic CD8+ T cells in vitiligo patients, we reasoned that agonistic PD-1/PD-L1 therapy might suppress melanocyte-reactive T cells, but concomitantly suppress regulatory T cells." (PMID 33240267, 2020). "It has been reported that TGP could promote re-pigmentation in vitiligo patients by improving the CD4+/CD8+ T lymphocyte ratio and the CD4+CD25+ Treg level in peripheral blood." (PMID 32410998, 2020). "Compared with healthy controls, the percentage of Tregs (CD4+Foxp3+ T cells) in the blood samples from vitiligo patients had a tendency to decrease, but with no statistical difference." (PMID 29974998, 2018). "On the other hand, some other studies had reported a nonsignificant increase in the peripheral percentage of CD4+CD25+ T cells in vitiligo patients compared to healthy controls." (PMID 26788051, 2015). "T cell tolerance in GILT−/−RAG1−/−TRP1Tg mice is partially mediated by Treg cells, as adoptive transfer of Treg cell-depleted CD4+ T cells, but not total CD4+ T cells, induces mild vitiligo in recipients." (PMID 24409178, 2013). "Homeostatic T cell expansion alone, in the absence of a melanocyte antigen-specific immune response, was insufficient for protective memory, as evidenced by a lack of tumor protection in CD4-depleted mice lacking vitiligo." (PMID 22046294, 2011). "Therefore, NK cell-derived exosomes may influence vitiligo development by affecting IFN-γ secretion and CD4+ T cell activation." (PMID 39040109, 2024). "Besides, AhR also regulates CD4+ TRM cell differentiation and function, which may conduce to immune protection, and tissue remodeling in vitiligo." (PMID 38361944, 2024). "T-cell expression of LOC100506314 was increased in vitiligo, especially CD4+, but not CD8+ T cells." (PMID 37731844, 2023). "Moreover, studies on vitiligo have not reported data on CD4+ helper or regulatory TRM cell subsets either." (PMID 31230406, 2019). "Total CD4 depletion does not affect vitiligo incidence or severity." (PMID 22046294, 2011). "Interestingly, the same study showed the highest frequency of CD4+/CD8+ CLA+ T cells producing IL-9 in patients with vitiligo in comparison with patients with AD, PSO, and AA and HC, pointing out for the first time a possible role for IL-9 on the physiopathology of vitiligo." (PMID 33833765, 2021). "Decreased percentage of peripheral CD4+CD25+ Tregs and decreased expression of FoxP3+ might impair the suppressive activity of Treg cells on cell proliferation with breakage of tolerance to melanocyte self-antigens which could contribute to the pathogenesis of vitiligo." (PMID 26788051, 2015). "However, since TRP1-specific CD4+ T cells have not been identified as pathologic in human vitiligo, this model may not accurately represent human vitiligo, but rather serves as a model of CD4+ T cell-mediated cutaneous autoimmunity." (PMID 24409178, 2013). "Indeed, similar proportions of mice developed vitiligo regardless of whether or not CD4 T cell help was present." (PMID 22046294, 2011). "A reduction in the frequency of PD-1 expressing CD3+, CD4+, CD8+, Th1, Th1/17, and Th17 cells was seen in patients not experiencing vitiligo during therapy." (PMID 37680638, 2023).
vitiligo (continued). "We found that the expression of LOC100506314 in significantly elevated in CD4+ T cells (1.94-fold; p=0.002), but not CD8+ T cells (1.18-fold, p=0.576) from patients with vitiligo compared with the controls." (PMID 37731844, 2023). "Each of circulating CD4+CD25+ Tregs percentage and FoxP3+ Tregs percentage did not correlate with patients' age, vitiligo disease duration, or VASI score." (PMID 26788051, 2015). "Although the immunopathologic mechanism is not precisely known, lesional CD4+ T cells with a Th17 phenotype, melanocyte-specific CD8+ T cells, and defects in regulatory T (Treg) cells are found in vitiligo patients." (PMID 24409178, 2013). "We have shown that post-surgical vitiligo is CD8 T cell-mediated, although a role for CD4 T cells was not specifically explored." (PMID 22046294, 2011). "A statistically significant negative correlation was observed between the percentage of CD4+CD25+ T cells and FoxP3+ Tregs in the peripheral blood of vitiligo patients and vitiligo disease activity according to VIDA score (r = −0.851, P < 0.001 and r = −0.512, P < 0.05, resp)." (PMID 26788051, 2015).